CCR8 (C-C motif chemokine receptor 8)
Diseases named in the same sentence as CCR8 in open-access papers (continued):
Sharing a sentence is not in itself a finding about the gene and the disease.
vitiligo (1 paper, 2024). Generalized well circumscribed patches of leukoderma that are generally distributed over symmetric body locations and is due to autoimmune destruction of melanocytes. "CCL22 activates the migration and activity of Tregs in vitiligo, which has been shown to be decreased in vitiligo skin, whereas no changes were found for CCR4, CCR5, CCR8 and cutaneous lymphocyte antigen (CLA)." (PMID 39274437, 2024).
tumor (226 papers, 2012 to 2026). "The chemokine receptors CCR6, CCR7, CXCR3, CXCR4, CXCR5, and CXCR6 have the highest expression across lymphocytes, and CCR8, a known hallmark of tumour infiltrating Treg cells, is exclusively expressed on Treg cells." (PMID 39915477, 2025). "The expression of CCR8 in MF/SS is associated with a Th2-prevalent cytokine environment, which favors tumor progression and immune evasion." (PMID 40861461, 2025). "Infiltration of CCR8+ Tregs in tumor tissue has been shown as a hallmark of many cancer types, with no report on HCC." (PMID 40186298, 2025). "In each of these tumor types, the expression of CCR8 correlated with Treg cell signature and was associated with poor prognosis." (PMID 38318526, 2024). "Our result showed that higher purine metabolism in tumor epithelial cells is strongly associated with markers of Treg activation (CCR8, FOXP3, and IL2RA) and levels of ADORA2A, encoding the well-known purine receptor A2AR, in Tregs." (PMID 39252976, 2024). "An upregulated expression of CCR8 in GC tissues was associated with tumor grade, nodal metastasis, and OS." (PMID 38169378, 2024). "CCR8 is mainly expressed in clonally expanded Tregs activated by tumor-associated antigens, with CCR8+ Tregs being an “effector-like” cell population with a stable anti-tumor immunosuppressive function." (PMID 38783281, 2024). "We not only found that TNFR2 and CCR8 were coexpressed in Tregs but also found that the increase in the number of TNFR2+CCR8+ Tregs was associated with tumour stage progression." (PMID 37935468, 2024). "In mouse models of colon, melanoma, breast, and urothelial cancer, research has shown that tumor-associated Tregs expressed high levels of CCR8." (PMID 36765704, 2023). "The fact that human skin and tumor Treg cells share the unique feature of expressing CCR8 suggests similar mechanisms underlying the control of CCR8 gene expression." (PMID 35158783, 2022). "Among the identified differences was highly increased expression of the chemokine (C‐C motif) receptor 8 (Ccr8) gene, encoding CCR8, within tumour‐infiltrating Treg cells as compared with Treg cells found in other tissues." (PMID 33838058, 2021). "CCL18 is a C-C chemokine mainly secreted by M2 type tumor associated macrophages which acts mainly by binding to its corresponding chemokine receptor CCR8." (PMID 33795528, 2021). "Whereas systemic ablation of Treg cells resulted in strikingly diminished tumour growth, growth of subcutaneously implanted tumours was unaffected by systemic CCR8 loss." (PMID 33838058, 2021). "CD4+LAIR2+ cells highly expressed Treg cell lineage markers, including IL2RA, CTLA4, TNFRSF18, ICOS, TIGIT, and tumor-associated Treg cell marker CCR8, consistent with CD4+ LAIR2+ cells being of Treg lineage and not recently activated T cells." (PMID 35008369, 2021). "Here, we formally tested the contribution of CCR8 to anti‐tumour immunity using genetic loss‐of‐function experiments in mice." (PMID 33838058, 2021). "CCR8 has been shown to be highly enriched in tumor Tregs and associated with a poor prognosis in several cancers." (PMID 32809975, 2020). "We observed that tumor-infiltrating FoxP3+ T cells highly express CCR8 and CXCR4, chemokine receptors associated respectively with memory cells and tumors." (PMID 22292042, 2012). "Instead, the tumor infiltrating FoxP3+ T cells highly express memory/tumor-associated CCR8 and CXCR4." (PMID 22292042, 2012). "Our data are in line with the role of CD137 as a relevant immunosuppressive molecule Treg-associated in the tumor microenvironment, different from what observed in periphery, and in agreement with an infiltrating CCR8+ICOS+ CD8+ Treg signature of disease progression found in NSCLC." (PMID 37898752, 2023). "In some murine models, CCR8+ Tregs highly express Treg-related molecules that are associated with suppressive functions, and anti-CCR8 antibody treatment reduces tumor volume and enhances anti-tumor immunity." (PMID 35354899, 2022).
tumor (continued). "Moreover, Tregs were confined in the tumor, inversely correlated with the amount of total T cells, and were associated with the expression of a chemokine receptor, CCR8 32,33." (PMID 33772139, 2021). "Moreover, high expression of CCR8 has been demonstrated as a signature of Treg cells that restrain immunity, of which their amount in tumours is significantly associated with poor prognosis in several cancers." (PMID 33531485, 2021). "Furthermore, in the present study, we found that, like the other two key genes, high expression of the CCR8 gene was significantly associated with an enrichment of Tregs in tumor tissue, which in turn predicted a better prognosis." (PMID 33692955, 2021). "However, whereas systemic ablation of Treg cells resulted in strikingly diminished tumour burden, growth of subcutaneously implanted tumours was unaffected by systemic CCR8 loss." (PMID 33838058, 2021). "In addition, the tumor-infiltrating Foxp3+ T-cells express high levels of memory/tumor-associated CCR8 and CXCR4 receptors, and antigen priming is required for the induction of this trafficking receptor phenotype." (PMID 24133490, 2013). "It is argued that given the intricate and redundant nature of the chemokine system, deficiency of CCR8 during initial embryonic development may cause compensation of its role by other chemokine receptors, resulting unchanged Treg phenotype in the tumor-bearing animals." (PMID 40186298, 2025). "Recruitment is driven mainly by CCL20-CCR6 and CCL22/CCL17-CCR4 signaling, while CCR8 marks highly suppressive tumor-resident Tregs." (PMID 42196608, 2026). "CCR8 has emerged as a biomarker for tumor-infiltrating Tregs which interfere with the action immune checkpoint inhibitors." (PMID 41302499, 2025). "Consistent with the simulation results, Treg-targeted monotherapy with the CCR8 inhibitor (IPG7236) produced only modest tumor control, reflecting the highly immunosuppressive nature of this model." (PMID 41568381, 2025). "Elevated TNF-α levels in the CRC tumor microenvironment promote the upregulation of CCR8 on Tregs via the TNFR2/NF-κB signaling pathway and FOXP3 transcription factor activity." (PMID 40308582, 2025). "Another tetravalent symmetric antibody, 2MW4691, targets CCR8, a tumor-resident Treg-specific marker, with low CTLA-4 affinity, eliminating intratumoral Tregs via ADCC without compromising CD8+ T cell activation." (PMID 41394821, 2025). "There is also a reports that targeting the glucocorticoid receptor -CCR8 axis in mice significantly suppressed tumor growth." (PMID 40786522, 2025). "The accumulation of lactic acid produced by glycolysis of tumor cells will cause CAR-T immunosuppression, and the upregulation of CD39, CD73 and CCR8 is an important mechanism." (PMID 39744577, 2025). "CCR8+ Tregs play a crucial role in the immune-suppressive tumor microenvironment in CRC by inhibiting the function of CD4+ Th and CD8+ T cells." (PMID 40308582, 2025). "In contrast, when tumor bearing mice were treated with 225Ac-anti-CCR8 mAb - there was statistically significant slowing down of CT26 and MC38 tumor growth with 14.8 kBq 225Ac-anti-CCR8 mAb and with 7.4 kBq 225Ac-anti-CCR8 mAb - of CT26 tumors." (PMID 41035646, 2025). "We believe that further investigation in different syngeneic tumor models and immunotherapy agents using anti-CCR8 RIT is warranted." (PMID 41035646, 2025). "To investigate the effects of 225Ac-anti-CCR8 RIT on the tumor growth as well as on the numbers of CCR8+ ti-Tregs, we performed RIT of CT26 and MC38 tumor bearing mice with 225Ac-anti-CCR8 mAb." (PMID 41035646, 2025). "Both tumors responded in a dose dependent manner to anti-CCR8 RIT alone via so called “bystander effect” on the tumor cells initiated by alpha-radiation emitted by 225Ac." (PMID 41035646, 2025). "The results indicated a positive relationship between the expression of CCR8 and Foxp3 and a higher level of CCR8 in primary tumor tissues relative to that in the adjacent normal tissue." (PMID 40186298, 2025).
tumor (continued). "Although these systems are highly relevant for studying immunosuppressive subtypes such as Treg-enriched TNBC, the applicability of CCR8-targeted interventions across other tumor types remains unexplored." (PMID 41568381, 2025). "A trend of initial expansion of total number of macrophages and of anti-tumor M1 macrophages was observed on Day 3 post treatment of tumor bearing mice with 7.4 kBq 225Ac-anti-CCR8 in both CT26 and MC38 tumors." (PMID 41035646, 2025). "Spatial analysis revealed that CCR8+ Tregs were distributed heterogeneously within the tumor and accumulated at the tumor invasion boundary." (PMID 41323783, 2025). "Shimon Sakaguchi has shown that targeted depletion of CCR4+ Tregs or CCR8+ Tregs can restore a robust, memory-driven anti-tumor immune response." (PMID 41368133, 2025). "Oxamate, a glycolysis inhibitor, has been shown to enhance CAR-T therapy efficacy by modulating tumor metabolism, specifically through the suppression of ectonucleotidases and inhibition of CCR8 lactylation." (PMID 40223940, 2025). "In mouse models, Treg depletion by delivering anti-CCR8 monoclonal antibodies re-invigorates tumour-specific effector memory T cells, resulting in profound tumour growth inhibition." (PMID 40801654, 2025). "Taken together, these observations of expansion of several immune cells in TME post 225Ac-anti-CCR8 RIT align with the decreased tumor growth observed after 225Ac-anti-CCR8 and CTLA-4 immunotherapy combination treatment." (PMID 41035646, 2025). "Here we investigated for the first time radioimmunotherapy (RIT) directed towards CCR8, a marker of tumor-infiltrating immunosuppressive T-regulatory cells (ti-Tregs) as a method to recover anti-tumor immunity followed by immunotherapy in CRC models." (PMID 41035646, 2025). "This lactate engages the receptor GPR81 on Tregs, stabilizing PD-1 expression and promoting CCR8-mediated chemotaxis, thereby further blunting anti-tumor immunity." (PMID 41487593, 2025). "The spatial analysis-generated dot plot of CCR8+ Tregs infiltrating into tumor tissues revealed an uneven distribution within the tumor, with high-density, low-density, and lymphocyte-deficient regions." (PMID 41323783, 2025). "Intratumoral CCR8+ Tregs exhibit enhanced immunosuppressive activity compared to peripheral Tregs, making CCR8 an attractive target for selectively depleting tumor-infiltrating Tregs while preserving systemic immune homeostasis." (PMID 40508202, 2025). "Anti-CCR8 antibody therapy, targeting tumor-infiltrating CCR8+ Tregs, has the potential to restore the function of CD4+ Th and CD8+ T cells in CRC, thereby inducing antitumor immunity." (PMID 40308582, 2025). "225Ac-anti-CCR8 RIT alone demonstrated effectiveness in CRC models but dramatic anti-tumor response was observed when it was combined with anti-CTLA-4 immunotherapy." (PMID 41035646, 2025). "When tumor size reached ~100 mm3 volume, mice received 7.4 kBq of 225Ac-anti-CCR8 and a loading dose (10 mg/kg, 200 μg) of CTLA-4 immunotherapy." (PMID 41035646, 2025). "Another innovative strategy involves anti-CCR8 antibodies targeting a Treg-specific marker in the tumor microenvironment." (PMID 41394821, 2025). "Tumor uptake of anti-CCR8 111In—IgG in both MC38 and CT26 tumors was ≥15% ID/g, which should translate into significant tumoricidal dose during radioimmunotherapy." (PMID 41302499, 2025). "To evaluate the presence of CCR8+ ti-Tregs in mouse tumor models, we performed intratumoral lymphocyte flow cytometry on tumors." (PMID 41035646, 2025). "Tumor immunohistochemistry post 225Ac-anti-CCR8 RIT showed ablation of CCR8+ ti-Tregs while flow cytometry analysis revealed CCR8-specific increased influx of effector CD8+ T cells, M1 macrophages and NK cells in comparison with 225Ac-control antibody." (PMID 41035646, 2025).
tumor (continued). "Preclinical studies using mouse tumor models have demonstrated that the depletion of CCR8+ Tregs through anti-CCR8 antibody administration resulted in significant tumor shrinkage 14,16-21." (PMID 41323783, 2025). "Therapeutic effects of an anti-CCR8 antibody to remove Tregs have been reported in mouse tumor models." (PMID 40053558, 2025). "Recent work has identified the surface C-C motif chemokine receptor 8 (CCR8) as a highly restricted marker for the tumor-infiltrating Tregs (ti-Tregs) within human and murine tumors." (PMID 41035646, 2025). "Inhibition or depletion of TNFR2 significantly reduces the infiltration of CCR8+ Tregs, which in turn suppresses tumor progression and improves the efficacy of anti-PD1 therapy." (PMID 40308582, 2025). "Regulatory T cells (Tregs) suppress antitumor immunity in the tumor microenvironment, and recent studies have identified C-C motif chemokine receptor 8 (CCR8) as a selective marker for tumor-infiltrating activated Tregs." (PMID 41323783, 2025). "Spatial analysis revealed that CCR8+ Tregs were preferentially localized at the tumor invasion front." (PMID 41323783, 2025). "Unlike other chemokines, such as CCR4, which is broadly expressed on Tregs in both tumoral and peripheral tissues, CCR8 expression appears to be largely restricted to tumor-infiltrating Tregs, potentially making it a safer immunotherapeutic target." (PMID 40508202, 2025). "Utilizing the CCL1-CCR8 axis, which recruits Treg cells to tumor sites, researchers have developed CCR8-CAR-T cells." (PMID 39136031, 2024). "By using a monoclonal antibody against CCR8, tumor Tregs were selectively eliminated, thereby curing established tumors in mice." (PMID 38509593, 2024). "The inhibition of CCR8 results in the improvement of antitumor immunity and patient survival rates by regulating tumor-resident regulatory T cells." (PMID 38721308, 2024). "CCR8 is distinctly upregulated in tumor-resident Tregs in breast, colon, and lung cancers compared with normal tissues." (PMID 39000453, 2024). "CCL18 expressed from TAMs plays a critical role in immune and inflammation responses, and its receptor CCR8 marks suppressive Treg cells within the tumor suggesting the immunosuppressive potential of the CCL18-CCR8 axis in bone metastatic ccRCC." (PMID 38281962, 2024). "The accumulated CCR8+ Tregs gradually formed a highly immunosuppressive microenvironment within the tumour tissues." (PMID 37935468, 2024). "CCR8+ Tregs have recently attracted attention as immunosuppressive cells that are highly concentrated in malignant tumor tissues compared with in peripheral blood and normal tissues in both humans and mice." (PMID 38783281, 2024). "CCR8 is preferentially expressed in lymphoid organs and participates in the recruitment of Tregs and Th2 cells to inflammatory and tumor sites." (PMID 38721308, 2024). "In both models, Tnfr2 depletion or TNFR2 blockade suppressed tumour progression by reducing CCR8+ Treg infiltration and thus augmented the efficacy of anti-PD1 therapy." (PMID 37935468, 2024). "Histone lactylation further amplifies the immunosuppressive environment by enhancing the transcription of ectonucleotidases CD39 and CD73, as well as the chemotactic receptor CCR8, which is a marker of tumor-infiltrating Tregs." (PMID 39766353, 2024). "In particular, blockade of CCR8 reduces the number of Tregs in the tumor microenvironment, thereby enhancing antitumor immune responses." (PMID 38915099, 2024). "It was unveiled in 2016 that CCR8 is specifically expressed on tumor-infiltrating regulatory T cells (TITRs) across a range of primary and metastatic human cancer types, including breast, lung, colon carcinoma, and melanoma." (PMID 38231448, 2024). "The blockade of CCR8 has also been found to reduce tumor burden, making it a promising target for drug treatments." (PMID 39409924, 2024). "Mouse studies have also corroborated that CCR8+ Tregs can suppress anti-tumor immunity via regulation of CD8+ T cell function." (PMID 38783281, 2024).